TNF (tumor necrosis factor)
Diseases named in the same sentence as TNF in open-access papers (continued):
Sharing a sentence is not in itself a finding about the gene and the disease.
chronic hepatitis B (45 papers, 2005 to 2025). "Genetic polymorphisms of several inflammatory cytokines, including TNF-α and IL-10, have been associated with chronic hepatitis B (CHB) progression, although with contradicting results." (PMID 36052277, 2022). "Very limited information exists in Thailand that reported the associations of IL-1β C-511 T and TNF-α G-308A polymorphisms with the risk of various cancers, especially in chronic hepatitis B virus infection-linked HCC." (PMID 30139338, 2018). "Moreover, another study performed in South Indian population concluded that TNF-α G308 was strongly associated with chronic hepatitis B." (PMID 27785252, 2013). "In a study on effect of telbivudine therapy on the cellular immune response in chronic hepatitis B, it was found that the decrease in serum HBV DNA levels was associated with an increase in IFN-γ and TNF-α production by HBV antigen-specific T cells." (PMID 37245038, 2023). "IL-17A can also significantly stimulate monocytes and DCs to express their ligand (IL-17R) and produce pro-inflammatory cytokines such as IL-1β, TNF-α, IL-6, etc., which are important for liver damage during progression of chronic hepatitis B." (PMID 33435966, 2021). "Many data showed the safety of anti-TNF-α in patients with chronic hepatitis B and C and in liver transplanted patients even if a strict follow-up and prophylaxis are recommended in well-defined subgroups." (PMID 30060508, 2018). "In this study, the major inflammatory cytokines expressed in chronic hepatitis, IL-6 and TNF-α, induced a marked decrease in microRNA-122 (miR-122) levels, and miR-122 expression was downregulated in the livers of chronic hepatitis B (CHB) patients." (PMID 26933995, 2016). "The result of this study demonstrates that supplementation of vitamin A at low and high dosages for short and long durations increases the CRP plasma concentrations on adults and vitamin A supplementation decreases the TNF-α concentrations in chronic hepatitis B on adults." (PMID 36496428, 2022). "Our patients with MDhi CD4 TEM and memory CD8 T cells exhibited functional exhaustion with reduced production of pro-inflammatory cytokines such as TNFα and IFNγ, which was also in line with other reports on chronic hepatitis B or long-term tumor antigen exposure." (PMID 35095881, 2021). "In chronic hepatitis B virus infection CD16+ subset of monocytes produces high levels of TNF, suggesting that this subset of monocytes may be closely related to liver damage in these HBV-infected patients." (PMID 24757288, 2014). "In concert with this speculation, genetic variants in MHC genes, the TNF-α gene, and the IFN-γ gene have been reported to be associated with chronic hepatitis B infection in humans." (PMID 22615863, 2012). "Interestingly, TNF-α and IL-1β, which are known to co-induce the other's expression, are both involved in chronic inflammatory diseases such as RA, chronic hepatitis B and C infection." (PMID 21858242, 2011). "In contrast another study has suggested that increased serum adiponectin in hepatic inflammatory activity which is an antagonizing TNF-α, may be a secondary to the response to hepatic injury in chronic hepatitis B." (PMID 20840785, 2010). "Immunomodulatory effects of CM and its components were also demonstrated in clinical studies of chronic hepatitis B and patients with HCV by increasing IFN-γ and Th1 but decreasing IL-4 and Th2, as well as TNF-α level." (PMID 35493477, 2022). "To examine the change in immune balance during the treatment of patients with chronic hepatitis B with entecavir and thymosin a1, we further analyzed the expression of immune factors such as IL-6, IL-12, IFN-γ, and TNF-α at the 12th, 24th, and 48th week of treatment cycles." (PMID 36596032, 2022).
chronic hepatitis B (continued). "The frequency of Tfh cells, serum pro-inflammatory cytokine (IL-12, IL-21, IL-17 and TNF) levels and IgG/M levels were investigated in HBV-ACLF (n = 36), serious chronic hepatitis B (n = 21), moderate chronic hepatitis B patients (n = 32) and healthy control (HC) subjects (n = 10)." (PMID 33868273, 2021). "The 2008 guidelines of the American College of Rheumatology (ACR), updated in 2012, do not recommend the use of anti-TNF-α in pharmacologically untreated chronic hepatitis B and treated with considerable damage to the liver (Child class-Pugh B and C)." (PMID 25549599, 2015). "Long-term safety and efficacy of anti-TNF agents in patients with chronic hepatitis B or hepatitis C are not known." (PMID 23606869, 2013). "While serum IL-2r (p = 0.002), IL-6 (p = 0.001), IL-8 (p = 0.013), PTH (p = 0.029), and CTX (p = 0.021) levels were higher in children with chronic hepatitis B than in healthy controls, there was no significant different in respect to serum IL-1β, TNF-α and osteocalcin levels." (PMID 16171525, 2005). "In contrast to previous observations in chronic hepatitis B, in PWH the percentage of IFNγ, TNFα and IL-2 producing CD8 T cells did not increase in the presence of MitoTempo and IL-12." (PMID 39356699, 2024). "Indeed, improving mitochondrial function by the anti-oxidant piperidine-nitroxide MitoTempo and IL-12 increased IFNγ release upon stimulation with HIV gag as well as CMV pp65, but did not affect the percentage of IFNγ, TNFα and IL-2 producing CD8 T cells as was observed in chronic hepatitis B." (PMID 39356699, 2024).
lymph node metastasis (45 papers, 2004 to 2026). "TNF-α expression and the total number of lymph node metastases were both identified as risk variables for the prognosis of BC metastasis by Cox regression analysis using general clinical pathological data." (PMID 38388665, 2024). "The study revealed positive associations between TNF-α expression and the rates of cellular proliferation, lymph node metastasis, microvessel density, and histological grade." (PMID 39609700, 2024). "Our analysis also showed that a higher degree of TNF-α was associated with greater lymph node metastasis and a higher degree of advanced stages of cancer in prostate adenocarcinoma, uterine corpus endometrial carcinoma, and bladder urothelial carcinoma." (PMID 37867861, 2023). "MiR-19a expression can be increased by TNF-α and is associated with lymph node metastasis and mesenchymal markers, suggesting a transition to the metastasis promoting EMT." (PMID 33918859, 2021). "In addition, IL-6 and IL-12P7 are associated with TNM staging and lymph node metastasis, while TNF-α is related to differentiation." (PMID 36226059, 2022). "We analysed the association between TNF-α-308G > A and clinical characteristics (age at diagnosis, BMI, tumour stage, tumour size, lymph node metastasis, distant metastasis, age at menarche, menopause and family history of cancer) by BC subtypes classified using IHC." (PMID 26165253, 2015). "In pleural metastatic patients, IFN-γ levels were lower (p = 0.026), while the levels of TNF-α were higher (p = 0.003) in patients with lymph node metastasis." (PMID 39502692, 2024). "Our study showed that low expression of TNF-α and IFN-γ was closely associated with lymph node metastasis." (PMID 36865498, 2023). "Serum levels of TNF-α and IL-6 were significantly increased when tumor length was > 5 cm, depth of invasion into the serosal layer, and lymph node metastasis occurred, consistent with previous findings." (PMID 37430251, 2023). "According to the findings, BCPs had a greater level of TNF-α in lymph node metastases than healthy persons." (PMID 35928364, 2022). "The obtained results also indicated a significantly increased level of TNF-α in the lymph node metastasis compared to healthy people." (PMID 35928364, 2022). "TNF-α levels, on the other hand, related to the degree of differentiation (t = -213, P <0.05) while IL-12P7 levels correlated with lymph node metastasis and TNM staging of patients (t = -2.713, 2.681, P <0.01)." (PMID 36226059, 2022). "Our results also show that leptin and TNF-α levels are positively correlated with lymph node metastasis status." (PMID 29088874, 2017). "A concomitant increase of TNF-α, a stimulus for HAS3 expression, with HAS3 expression was not only associated with lymph node metastasis but also negated clinical outcome." (PMID 28107185, 2017). "The inflammatory cytokine tumour necrosis factor (TNF)-α promotes tumour progression and lymph node metastasis in gallbladder cancer (GBC)." (PMID 27009073, 2016). "The group of patients with lymph node metastases or bone metastases had similar IL-6 and TNF-α levels (P=0.31 and P=0.28), which were higher than those in the group with localised disease (P<0.001)." (PMID 15150588, 2004). "Notably, in the context of PCa, TNF-α has been implicated in promoting cell migration via the upregulation of CCR7, particularly in cases of lymph node metastasis." (PMID 38484140, 2024). "Moreover, we found that patients with lymph node metastasis had higher baseline TNF-α levels and they were related to poorer PFS as well." (PMID 39502692, 2024). "According to the Cox regression analysis model, the occurrence of postoperative distant metastasis of BC was regarded as the dependent variable, and indices such as PR, lymph node metastasis grade and TNF-α score in the univariate analysis were regarded as independent variables." (PMID 38388665, 2024).
lymph node metastasis (continued). "The results showed that TNF-α (RR = 1.123, 95% CI 1.052–1.199; P < 0.001), a number of lymph node metastases of 4–9 (RR = 2.763, 95% CI 1.512–5.048; P = 0.001), and a number of lymph nodes ≥ 10 (RR = 3.088, 95% CI 1.756–5.432; P < 0.001) were risk factors for distant metastasis after BC." (PMID 38388665, 2024). "Furthermore, this percentage of high TNF mRNA expressing Prostate Adenocarcinoma patients (altered group; Log2 Ratio = 3.18; p = 1.67E-18) also presented a greater level of lymph node metastasis than the unaltered group." (PMID 37867861, 2023). "In addition, the enrichment score of TNF signaling was negatively correlated with lymph node metastasis in BLCA patients (P<0.05)." (PMID 37324016, 2023). "A high TNF-α concentration inhibited PC3 proliferation, a low TNF-α concentration caused an upregulation of C-C chemokine receptor, which is significantly associated with lymph node metastasis." (PMID 35740575, 2022). "The results indicated that lymph node metastasis and TNM staging are both independent risk factors connected to IL-6 and IL-12P7; the degree of differentiation being an independent risk factor (P <0.01) connected with TNF-α level (P <0.01)." (PMID 36226059, 2022). "However, deceased patients showed a higher TNF-α immunostaining in tumour (p=0.032) and lymph node metastasis (p=0.009) compared to living patients." (PMID 31870104, 2019). "The NF-kB immunostaining was significantly higher in tumour and lymph node metastasis than in MSR squamous epithelium (p<0.001), and the TNF-α immunostaining was significantly higher in tumour than in lymph node metastasis and MSR squamous epithelium (p<0.001)." (PMID 31870104, 2019). "The group with lymph node metastasis exhibited significant enrichment in the platinum drug resistance and cell cycle pathways, while the group without lymph node metastasis showed enrichment in pathways like TNF signaling, PI3K‐Akt signaling, NF‐kappa B signaling, and nucleocytoplasmic transport." (PMID 39206584, 2024). "The expression levels of IL-2 (P ═ 0.010), IL-4 (P ═ 0.028), IL-10 (P ═ 0.011), IL-12p70 (P ═ 0.034), IL-17 (P ═ 0.024), tumor necrosis factor (TNF)-α (P ═ 0.003), and interferon (IFN)-γ (P ═ 0.007) were related to lymph node metastasis." (PMID 38920620, 2024). "The results indicated a significant correlation between IL-2 (P ═ 0.025), IL-4 (P ═ 0.005), IL-8 (P ═ 0.009), IL-10 (P ═ 0.017), IL-12p70 (P ═ 0.002), IL-17 (P < 0.001), TNF-α (P < 0.001), and IFN-γ (P ═ 0.026) and lymph node metastasis." (PMID 38920620, 2024). "Meanwhile, TNF-α and IFN-γ protein expressions in the cancer tissues were significantly low in patients with lymph node metastasis (P < 0.05)." (PMID 36865498, 2023). "The TNF rs361525 wild-type genotype was significantly related to stage III-IV disease and the COX-2 rs20417 wild-type genotype was significantly related to lymph node metastasis." (PMID 34150619, 2021). "Additionally, TNF-α content was markedly greater in stage III carcinoma patients compared to controls (P < 0.01) and was positively correlated to lymph node metastasis (P < 0.01)." (PMID 40906676, 2025). "By analyzing the protein expression of METTL1, WDR4, and TNF-α in PTC tumor tissues, we found that PTC tissues from patients with lymph node metastasis had higher METTL1, WDR4, and TNF-α expression than those from patients without lymph node metastasis did." (PMID 40360483, 2025). "Furthermore, the expression of TNF-α and TNFR2 was observed in uncommon subtypes of BC, specifically invasive micropapillary carcinoma (IMPC), which is known for its high incidence of lymph node metastasis and unfavorable prognosis." (PMID 39609700, 2024). "The group without lymph node metastasis showed enrichment in the TNF signaling pathway, PI3K‐Akt signaling pathway, and proteoglycans in cancer pathways, possibly associated with a better prognosis." (PMID 39206584, 2024).
lymph node metastasis (continued). "The results showed that there is a statistically significant correlation between the expression level of IL-2 (P ═ 0.010), IL-4 (P ═ 0.028), IL-10 (P ═ 0.011), IL-12p70 (P ═ 0.034), IL-17 (P ═ 0.024), TNF-α (P ═ 0.003), and IFN-γ (P ═ 0.007) and lymph node metastasis." (PMID 38920620, 2024). "Overexpression of Tim-3 may play an important role in the relationship between TNF-α and IFN-γ secretion and worse clinicopathological parameters such as lymph node metastasis." (PMID 36865498, 2023). "TNF-α did not have significantly different levels between the N stages, even a slight decrease in levels between patients without lymph node metastases (N0) and those with lymph node metastases (N1-2)." (PMID 38137862, 2023). "While TIM-3 protein expression in cancer tissues of patients with lymph node metastasis was higher than in patients without metastasis, the expression of TNF-α and IFN-γ was lower (P < 0.05)." (PMID 36865498, 2023). "This study showed that TNF-α and IFN-γ synergistically promoted lymph node metastasis." (PMID 36865498, 2023). "Multi-factor analysis of IL-6, TNF-α and IL-12P7 levels in patients refers to three factors (lymph node metastasis, historical score and TNM staging) as the argument, which uses the expression of IL-6, TNF-α and IL-12P7 as the dependent variable by multi-step regression analysis." (PMID 36226059, 2022). "Leptin and TNF-α levels were also significantly higher in lymph node metastasis (LNM) positive cases than in LNM negative cases, with a pooled SMD of 0.80 (95% CI, 0.45, 1.14; P < 0.00001) and 0.63 (95% CI, 0.30, 0.96; P = 0.0002) respectively." (PMID 29088874, 2017). "Interestingly, the expressions of TNF-α and IFN-γ in cancer tissues of patients with no lymph node metastasis were higher than those in patients with lymph node metastasis." (PMID 36865498, 2023).
schistosomiasis (45 papers, 2011 to 2025). An infectious disease caused by parasitic trematodes of the genus Schistosoma that colonize human blood vessels and release eggs that can cause granulomatous reactions leading to acute (swimmer's itch or acute schistosomiasis syndrome) or chronic disease. "In humans, although high TNF-α levels are associated with severe hepatic fibrosis, it is still unclear which cytokines are involved in the progression of schistosomiasis pathology." (PMID 36820674, 2023). "Higher TNF-α and lower IL-10 levels were negatively associated with infection and may confer protection against schistosomiasis." (PMID 34007813, 2021). "We therefore hypothesised that the IL-10 -1082 A allele and TNF-α 308 A allele, as well as genotypes with these alleles, would be associated with reduced susceptibility to schistosomiasis in our study population." (PMID 34485462, 2020). "Notably, elevated TNF levels can occur during acute schistosomiasis and severe pathology is associated with elevated circulating levels of TNF and TNF receptors (TNFRs)." (PMID 31341177, 2019). "Intriguingly, as another Th1-related cytokine, Tumor necrosis alpha (TNF-α) at higher levels in supernatants from patient's whole-blood cultures, rather strongly associated with an increased risk of periportal fibrosis during hepatosplenic schistosomiasis." (PMID 30546364, 2018). "Among 58 participants, 33 (57%) had schistosomiasis, which was associated with elevated levels of interleukin (IL)-10 (0.32 vs. 0.19 pg/ml; p = 0.038) and a trend toward increased tumour necrosis factor (TNF) (1.73 vs. 1.42 pg/ml; p = 0.081)." (PMID 30453907, 2018). "The high levels of TNF throughout the period were an indicator that the children may have had a prolonged infection and were at risk of development of pathology associated with schistosomiasis." (PMID 34239575, 2021). "Additionally, there was a positive association between serum levels of TNF-α and S. mansoni parasite burden, which suggests that this cytokine may contribute to the liver pathology observed in schistosomiasis." (PMID 23320145, 2012). "The polymorphic TNF-α (-G308A) can be a risk factor for UGIB, in addition to being a potentially predictive factor for the severity of UGIB in schistosomiasis." (PMID 36820674, 2023). "Cytokines such as TNF-α, IL-1β, IL-6, IL-4, and IL-10, among others, show increased serum levels during schistosomiasis, reflecting the polarization and complexity between Th1 and Th2 immune responses." (PMID 38239348, 2023). "We evaluated the association between polymorphisms in the tumor necrosis factor alpha (TNF-α) (-G308A) gene and upper gastrointestinal bleeding (UGIB) in schistosomiasis." (PMID 36820674, 2023). "In human schistosomiasis, S. mansoni and S. haematobium up-regulate IL-1ra, IL-10, and TNF-α, whereas S. japonicum induces the up-regulation of several cytokines, including IL-1β, IL-1ra, IL-2, IL-6, IL-8, IL-10, IL-15, IL-18, and TNF-α." (PMID 36339337, 2022). "It is well known that circulating TNF-α levels are strongly influenced by liver inflammation in schistosomiasis, but our results indicate that the tissue levels of this cytokine are not influenced at this stage of infection or by its increase in serum." (PMID 34303703, 2021). "Mice in the model group exhibited high TNF-α and IL-6 protein levels owing to schistosomiasis-induced liver tissue damage." (PMID 33553120, 2020). "Cytokines, such as TNF-α and IL-6, play an essential role in the progression of the schistosomiasis." (PMID 33553120, 2020). "Cytokines such as TNF-α, IL-6, and IL-1 β, which are significant mediators of tissue damage, play an essential role in the progression of schistosomiasis." (PMID 33553120, 2020). "Quantification of inflammatory mediators in liver fragments from a chronic model of schistosomiasis showed a significant decrease in TNF-α, IL-1β (P < 0.01) and IL-6 (P < 0.001) levels after cell therapy." (PMID 31015492, 2019).